CD4 (CD4 molecule)
Diseases named in the same sentence as CD4 in open-access papers (continued):
Sharing a sentence is not in itself a finding about the gene and the disease.
infection (continued). "In this study, CD4+ T cell depletion was performed using antibody before and after infection and was shown to modify parasite biomass to the same extent as CD8+ T cell depletion." (PMID 21494565, 2011). "CD4+ T cells play an important role in the initiation of immune responses against an infection by providing help to other cells and by taking on a variety of effector functions during immune reactions." (PMID 22102924, 2011). "Our data reveal that as infection progressed a concurrent depletion of the absolute number of CD4+/CCR5+ cells and CD4+/CXCR4+ cells occurred when comparing Early and Late stage groups." (PMID 21655330, 2011). "For instance, in analysis of cytokine secretion from endogenous airway memory CD4+ T cells, we found a significant increase in IL-10 expression during secondary infection." (PMID 21647373, 2011). "Depletion of Th17 cells and their precursors is mediated by direct infection of target cells, bystander apoptosis or a combination of mechanisms like other infected CD4+ T cells." (PMID 21994747, 2011). "CA-074Me treatment of C33A cells at 50 μM enhanced the CD4-independent infection about 5 times, like TE671 cells." (PMID 21541353, 2011). "Collectively these data demonstrate that upon infection with L. mexicana, initial lesion growth in BALB/c mice is dependent on non-T cell population(s) responsive to IL-4/IL-13 while progressive infection is dependent on CD4+ T cells responsive to IL-4." (PMID 21245915, 2011). "Multiple receptors and mechanisms are involved in the binding and uptake of HIV-1 and infection by C-HIV can be CD4 independent." (PMID 21853149, 2011). "After excluding women with discordant BED and AI results, and those with CD4<200 cells/μl and therefore probable long-term infection, 11% (21/190) of HIV-positive FSW were classified by both the BED-CEIA and AI as having recently acquired HIV infection." (PMID 21949704, 2011). "Both activated and “ostensibly resting” CD4+ T cells are involved in the early stages of infection in the GALT." (PMID 21284901, 2011). "Median time from infection to the first laboratory measurements (CD4, HIV-RNA, HIV-DNA) and cART initiation was 1.6 months [1.4; 1.8]." (PMID 22102898, 2011). "CHS and WT CD4+ T cells were incubated with virus for 4 h, unbound virus was removed by washing and infection was measured by luciferase activity after 24 h." (PMID 21909273, 2011). "In this study, the role of CD4+ T cells and acquired responses during a primary infection with M. mycoides subsp." (PMID 21663697, 2011). "Cystatin C expression also enhanced the CD4-dependent infection, but the effect on the CD4-dependent infection was less than that on the CD4-independent infection." (PMID 21541353, 2011). "We infected the BLT mice with 50,000 TCID50 of either WT or V38E virus and followed them for virus replication and CD4 decline, by measurement of CD4 T cell percentage from before infection to 8 weeks post infection." (PMID 21255440, 2011). "Here we show that HIV-1 proteins associate with cellular compartments that are involved in regulated secretion and that CD4+ T cells from patients with a genetic defect in this pathway are less able to support spreading infection." (PMID 21909273, 2011). "Severe SA infections are generally described among the patients with CD4+ lymphocytes less than 100 cells/mm3." (PMID 22022439, 2011). "When the cathepsin B-overexpressing 293T cells were treated with CA-074Me at 25 μM, the CD4-independent vector infection was enhanced, as in HeLa and TE671 cells." (PMID 21541353, 2011). "CD4+ T cell counts rebound to a degree but remain lower than pre-infection levels as they gradually decline throughout the course of the disease." (PMID 21364928, 2011). "In ex vivo experiments and in autopsied tissues infection was revealed in CD4 T lymphocytes and in LCs." (PMID 21284905, 2011).
infection (continued). "Co-cultures of infected EZP CD4+ T-cell cultures with untransduced EZP CD8+ T cells contained many SIV Gag staining cells (43% in this representative experiment) 7 days after infection." (PMID 21886812, 2011). "The balance between these two sets of CD4+ effector cells allows for the tuning of the immune response to the state of infection." (PMID 21747996, 2011). "On the same day, splenocytes of LCMV-infected BL/6 mice (17 days post infection) were harvested, purified for CD4+ T cells by MACS and adoptively transferred i.v. to these naïve CD8-depleted BL/6 mice." (PMID 21966366, 2011). "The development of protection against invasive infection required both CD4 cells and antibody but the precise mechanisms involved have not been clearly defined." (PMID 22003400, 2011). "The younger age and significantly higher CD4 cell numbers among those estimated to have recent infection provide some evidence for the veracity of the BED assays." (PMID 21698125, 2011). "Enhancement of infection in vitro of permissive cells that express DC-SIGN was greater for the CD4-dependent HIV-1 IIIB strain than for the CD4-independent strain HIV-1 IIIBx." (PMID 22163292, 2011). "In subsequent studies, infection of CD4+ T cell specific (LckcreIL-4Rα−/lox) IL-4Rα−/− mice with 5×106L." (PMID 21245915, 2011). "At genital mucosa it is possible that antigen-specific T cells responses that involve DCs interacting with α4β7+ CD4+ T cells promote infection of those CD4+ T cells." (PMID 21284901, 2011). "Following infection of CCL19-treated CD4+ T-cells with NL4.3 with enhanced green fluorescent protein (EGFP) inserted into the nef open reading frame (NL4.3- Δnef-EGFP), there was no EGFP expression detected." (PMID 21992606, 2011). "Trafficking of CD4+ T cells has been reported in the CNS during infection of other neurotropic viruses." (PMID 22007152, 2011). "The frequency of IFNγ+ CD4+ T cells increased in the later stages of infection and by d28 pi, 39.1% of CD4+ T cells in the liver and 7.6% in the spleen of WT mice were producing IFNγ." (PMID 21253574, 2011). "The X4-ZFN group exhibited a mean 1.1 log CD4 count protection by day 14 post infection (p = .05 for a parametric t-test)." (PMID 21533216, 2011). "The more efficient capture of virus by DC-SIGN leads to higher levels of infection but, in addition, for a wholly CD4-dependent strain the relative rate of infection is increased." (PMID 22163292, 2011). "In vaccinated and unvaccinated animals specific CD4+ T cell responses in the lung peaked after one month of infection and then declined." (PMID 22162757, 2011). "In the young age group where infection was rising, the proportion of Treg of the total CD4+ T cell population increased significantly with increasing infection intensity." (PMID 21347311, 2011). "We suggest that at low concentrations, soluble DC-SIGN but not Langerin (or HHA) stabilises interaction of gp120 on the virus surface with CD4 to enhance infection." (PMID 22163292, 2011). "Hybridoma cells between HeLa and 293T cells were as susceptible to the mNDK vector infection as 293T cells, indicating that HeLa cells lack a cellular factor(s) required for the CD4-independent mNDK vector infection." (PMID 21541353, 2011). "Both human and an SIV/macaque model studies indicate that during the first days of infection, termed the “eclipse phase”, low levels of viral replication occur, primarily in suboptimally activated memory CD4+ T cells in the genital mucosa." (PMID 21383973, 2011). "It was recently shown that IFNγ-secreting CD4 T cells are necessary for the migration of herpes simplex virus-specific CD8 T cells to the site of infection." (PMID 21901102, 2011). "DCs do not usually become productively infected with HIV-1 even in vitro, although they do express the appropriate HIV-1 entry receptors (CD4 and a chemokine co-receptor) and it generally held that productive infection by HIV-1 is a property of immature mDCs." (PMID 21247613, 2011).
infection (continued). "Highest numbers of CD4+ T cells were detected at an earlier time post infection than CD8+ T cells, and a great increase was seen in the CD4+ T cells population, while CD8+ T cells increased to a lesser degree in DNA immunized ducks." (PMID 21569289, 2011). "R5 viruses dominate the early stages of infection, largely infecting activated memory CD4+ T cells in the draining lymphoid tissue, particularly the GALT." (PMID 21284901, 2011). "The mechanism for CD4+ T cell rebound is currently unclear, but this rebound has been seen in some studies that track infection for at least several months." (PMID 21835012, 2011). "Third, in contrast to HIV-1, VSV G-pseudotyped HIV particles, which constitutively enter through endocytosis, exhibit different requirements for HIV-1 accessory proteins for infection, and strikingly, fail to infect resting CD4+ T cells." (PMID 22145853, 2011). "Mice infected with CRM-0019 showed significant reduced numbers of lung and spleen TNFα–expressing CD4+ T cells by day 30 of infection compared to the reference strain." (PMID 21931831, 2011). "Since the model assumes a CD4+ T cell count of 800 cells/uL at the time of infection, we used time of diagnosis for all values > = 800 to avoid estimation of infection dates later than HIV+ diagnosis dates." (PMID 22110765, 2011). "In the acute phase of infection, the virus depletes CD4+ T cells in the mucosal tissue of the gut as they represent the “ideal targets” of the virus (activated CD4+ T cells, near the front door of the virus, at the lining of the vagina or anus)." (PMID 21994747, 2011). "In the case of CD4-independent infection, enhanced intrinsic reactivity increases the probability that the unliganded HIV-1 envelope glycoproteins will make the transition to the pre-hairpin intermediate without the assistance of CD4." (PMID 21731494, 2011). "Of the 60 subjects included, 56 (27 hungry/high infection and 29 harvest/low infection) CD4+ T cell and 59 (29 hungry/high infection and 30 harvest/low infection) CD8+ T cell samples had complete sjTREC data." (PMID 21676219, 2011). "Whole blood was collected in EDTA for CD4 counts, viral load, serological estimation of duration of infection using the BED Calypte assay and genotyping for drug resistance." (PMID 21698125, 2011). "After the establishment of productive infection, the presence of CD4 has been found to disrupt the life cycle of the virus, including the possibility of super-infection, premature binding of CD4 to nascent virus particles, and inhibition of virus release." (PMID 22174949, 2011). "Infections of non-, or slowly-dividing cells can occur in vivo (e.g. naïve CD4+ T-cells, resting memory CD4+ T cells, and macrophages)." (PMID 21722380, 2011). "Both proportions and absolute numbers of CD4+FoxP3+Tregs significantly increased within the mLN during acute infection, when anti-egg Th2 responses are at their peak." (PMID 21858239, 2011). "Inhibition of cathepsin B by the cystatin C expression or by the CA-074Me treatment increases the CD4-independent infection by suppressing the viral particle degradation." (PMID 21541353, 2011). "Meanwhile, the proportion of the Treg cells in the total splenic CD4+ T cell population showed a continuous increase after infection." (PMID 22102924, 2011). "Each C57BL/6 mouse had between 200 and 250 2W:I-Ab-specific CD4+ T cells before infection, and these cells expressed small amounts of CD44 (CD44Lo) on the surface as expected for naïve cells." (PMID 21966268, 2011). "The TLR4 signal activation also attenuated the CD4-independent vector infection by enhancing cathepsin B expression." (PMID 21541353, 2011). "Three days after the last infection, mice were euthanized and enriched CD4+2W:I-Ab+ T cells from spleen, cervical lymph nodes (CLN), and NALT were analyzed." (PMID 21966268, 2011). "The migration property of DCs has been hijacked by HIV-1 for viral dissemination to CD4+ T cells by a process that is known as trans-infection." (PMID 22110688, 2011).
infection (continued). "Since Ly6Chi monocytes have similar phenotype to myeloid-derived suppressor cells, which expand during cancer, inflammation, and infection, we tested their ability to suppress CD4+ T cells." (PMID 21383977, 2011). "Here, we show that increased numbers of CD4+CD25+CD127low Treg correlate to the levels of gp120 in the LN at 12 weeks post infection and that the LN resident Tregs are in part responsible for the dampening of ex vivo CD8 IFN-γ responses against Gag antigen." (PMID 21483689, 2011). "Wereasoned that, if M. tuberculosis-infected cells do not presentantigens efficiently to effector T cells in the lungs, then the frequency ofactivation of effector functions of CD4+ cells would also be lowat the site of infection." (PMID 21637811, 2011). "During the infection, antibodies elicited against T. cruzi antigens help to control blood circulating parasite and specific CD4+ and CD8+ T cells act against intracellular forms." (PMID 21886854, 2011). "Given the overlap in the function of MIP-1α, MIP-1β and RANTES, these studies suggest a potential role for RANTES early in T cell responses to infection possibly via CD4 help." (PMID 21814510, 2011). "The infected U87.CD4.CXCR4 cells were harvested at day 5 post-infection, and HIV-1 DNA were extracted for PCR amplification employing subtype-specific oligonucleotide primers to detect, amplify, and quantify env recombinants in HIV-1 dual infections." (PMID 21232148, 2011). "This shows that HeLa cells lack a cellular factor(s) that is required for the CD4-independent mNDK vector infection." (PMID 21541353, 2011). "Reactivation of latently infected resting CD4+ T cells can then re-establish infection once cART is stopped." (PMID 21255462, 2011). "Compared to the CD4+T cells responses in the spleen, that of the mesenteric lymphocytes showed a more rapid increase of Th17 cells during the first three weeks post-infection and a weaker Th1 response throughout infection." (PMID 22102924, 2011). "The CD4+:CD8+ ratio was similar for both harvest/low infection and hungry/high infection season born, at 1.6 and 1.5 respectively." (PMID 21676219, 2011). "Specifically, during infection, the number of CD4 cells increases to fight infection; more target cells means more infected cells, producing more virus, increasing the viral load to a detectable level." (PMID 21552334, 2011). "In summary, these studies demonstrate rapid responsiveness of a local population of CD4+ T cells in the lung airway at the time of secondary infection." (PMID 21647373, 2011). "To address this, we compared the phenotype, function and proliferation of CD4+ T cells in various organs during secondary infection." (PMID 21647373, 2011). "The baseline CD4 count was determined for each animal as the average value of two pre-infection time points." (PMID 21359149, 2011). "IFNγ–producing CD4+ T cells were already detected at d14 of infection in both the liver and spleen of WT mice, although still at low frequency." (PMID 21253574, 2011). "Cystatin C, which inhibits cystein cathepsin proteases, was isolated as an enhancer of the CD4-independent mNDK vector infection in HeLa cells." (PMID 21541353, 2011). "Second, resting CD4 T cells are likely the primary target cell population early in infection, and these cells produce virus at a substantially lower rate than the activated CD4 T cells that are the major source of virus in the disseminated acute phase." (PMID 22125483, 2011). "The H66N change decreases the efficiency of CD4-independent infection; by contrast, the S375W change exerted little specific impact on CD4 independence." (PMID 21731494, 2011). "Such capture of virus can facilitate both direct infection of dendritic cells (cis-infection) and infection of interacting CD4 T cells (trans-infection)." (PMID 21284905, 2011).
infection (continued). "The early phase of the response finishes after a week of infection, with the elimination of a large proportion of CD4+ T cells, which then gives opportunity to the development of acquired immunity." (PMID 21814579, 2011). "In order to have power to detect correlations, we have considered a large sample set of purified CD4+ T cells from individuals with known date of infection and carefully determined viral load results." (PMID 20195503, 2010). "In vitro infection of CD4+-T cells with HIV also results in downregulation of IFNγ expression, while commencement of HIV-infected patients on antiretroviral therapy leads to an increase in IFNγ production." (PMID 21048923, 2010). "All three groups had comparable mean CD4+ T cell numbers at study end; mean levels which were lower than pre-infection levels." (PMID 20085648, 2010). "To identify suitable target cells for coculture infection experiments, we examined Luc transduction of established cell lines and primary activated CD4+ T cells by coculture with Jurkat cells transfected with HTLV-1 vectors." (PMID 20195464, 2010). "Bacteria displaying MIP1α reduced infectivity by 35–78% depending on the specific subtype while CD4 display reduced infection by as much as 56%." (PMID 20442778, 2010). "Three days post infection with Ye the number of splenic CD8α+ and CD4+ DCs was reduced by 50% and 90%, respectively." (PMID 21124820, 2010). "The initiation of antiviral therapy 4 hours after infection prevented CD4+ T cell depletion in lung tissues." (PMID 20485497, 2010). "Together, these data suggest that the SmCB1-specific IgE response during pre-patent infection is dependent on a concomitant IL-4-producing CD4+ T helper response to worm antigens." (PMID 21078176, 2010). "Under these circumstances, iDCs would preferentially transmit de novo synthesized virus upon productive infection, and the mDC-enhanced trans-infection ability would play a key role in the lymph nodes, mediating viral transmission to new target CD4+ T cells." (PMID 20360840, 2010). "Infection of T CD4+ cells begins with the binding of the viral envelope trimeric glycoprotein gp120 with the CD4 receptor and a chemokine receptor (CCR5 or CXCR4) of the host cell." (PMID 20352107, 2010). "R5 mac-tropism also correlated with the capacity of envelopes to infect cells via low levels of CD4 consistent with infection of macrophages that express substantially lower amounts of CD4 compared to T-cells." (PMID 20507591, 2010). "Based on an experimental Ye mouse infection model it was demonstrated that CD4+ and CD8+ T cells are required for control of Ye infection." (PMID 21124820, 2010). "Virions are mobilized to the lymph nodes either via attachment of the HIV Gp120 to the DC-SIGN receptor expressed on dendritic cells (DCs) or by direct infection of DCs within epithelia via CD4 and CCR5 receptors." (PMID 20967291, 2010). "An important feature of HIS mice is their ability to be infected by human-specific pathogens such as HIV, which depletes CD4+ T cells following infection." (PMID 20700454, 2010). "A recent report suggests that responses to several CD4 epitopes can be detected during the acute infection stage but are subsequently lost in progressor patients, which supports the idea of a rapid culling of the CD4 repertoire." (PMID 20195518, 2010). "The diagnosis rested upon identifying atypical infections, in otherwise healthy individuals, who had persistent CD4+ lymphocytopenia (less than 300 cells per micro-liter) and were non-immunosuppressed and were HIV negative." (PMID 20806085, 2010). "CFSE-labelled MSP-1-specific Tg CD4 T cells were injected into chronically infected or infected and drug-cured mice at day 45 and 60 post-infection, and recovered and analyzed after 3 days." (PMID 21124875, 2010). "Of note, after recovery of the patients, the percentage of CD4+CD11b+ and CD4+CD28− declined, indicative of a causal relationship between infection and T cell activation." (PMID 21151520, 2010).